MUC16 (mucin 16, cell surface associated)
Description:
Thought to provide a protective, lubricating barrier against particles and infectious agents at mucosal surfaces.
Synonyms: CA-125; CA125; FLJ14303
Tractability: Antibody: an approved drug acts on it; its Gene Ontology location is reachable by antibodies, with high confidence; UniProt places it where antibodies can reach, with medium confidence; UniProt predicts a signal peptide or a membrane-spanning region. PROTAC: ubiquitination databases record sites on it. Other modalities: a drug acting on it is in phase 2 or 3 trials.
Safety:
Unwanted effects reported when the protein is acted on. In parentheses: how it was acted on, where the effect was seen, and who reports it.
nausea and vomiting (source: ClinPGx)
Gene: Protein-coding gene on chromosome 19 (8,848,844 to 9,010,390, reverse strand). Ensembl gene ENSG00000181143.
Subcellular location: Cell membrane; Secreted, extracellular space
Pathways (Reactome):
Disease: Defective C1GALT1C1 causes TNPS; Defective GALNT12 causes CRCS1; Defective GALNT3 causes HFTC
Metabolism of proteins: O-linked glycosylation of mucins; Termination of O-glycan biosynthesis
Immune System: Dectin-2 family
Gene Ontology:
Molecular function: protein binding
Biological process: cell adhesion
Cellular component: external side of plasma membrane; extracellular exosome; vesicle; Golgi lumen; plasma membrane; extracellular region
Genetic constraint (gnomAD): Loss-of-function variants: 619 observed, 840.39 expected, observed/expected ratio (o/e) 0.74, 90% interval 0.69 to 0.79. The upper end of that interval is the gene's LOEUF score, 0.79, which puts it in group 3 of 6, group 1 being the genes least tolerant of losing a copy. Missense variants: 19,822 observed, 18,002 expected, observed/expected ratio (o/e) 1.1, 90% interval 1.09 to 1.11. Synonymous variants: 7,303 observed, 6,839.9 expected, observed/expected ratio (o/e) 1.07, 90% interval 1.05 to 1.09.
Homologues: Orthologues: mouse Muc16 (20% identical).
Diseases named in the same sentence as MUC16 in open-access papers:
MUC16 is named in the same sentence as 255 diseases in open-access papers, as found by Europe PMC text mining. Sharing a sentence is not in itself a finding about the gene and the disease. The quoted sentences say what the papers report.
ovarian carcinoma (461 papers, 2004 to 2026). A malignant neoplasm originating from the surface ovarian epithelium. "The presence of MUC16 splice variants in ovarian cancer and other cancers is still an area of active investigation, but some intriguing evidence suggests that mucin splice variants are a hallmark of cancer." (PMID 40361385, 2025). "One of the most notable diagnostic biomarkers is MUC16, which is widely used in ovarian cancer assessment, however, it has limited use as an independent endpoint for drug treatment selection." (PMID 40836974, 2024). "The other malignant population expressing CA125 (MUC16), the most common biomarker for ovarian cancer, is associated with a decrease in the number of tumor-infiltrating cytotoxic T lymphocytes (CTLs)." (PMID 35892844, 2022). "CA125 is a membrane associated glycoprotein encoded by the MUC16 gene which is often elevated in ovarian cancer, although it is also raised in up to 50% of CCA cases." (PMID 34660269, 2021). "CA-125, encoded by the MUC16 gene, is highly expressed in most ovarian cancer cells and thus serves as a tumor marker for monitoring disease progression or treatment response in ovarian cancer patients." (PMID 34503075, 2021). "MUC16 has been extensively used as a biomarker for ovarian cancer, and its expression has been associated with disease progression and has proven valuable in both detection and disease monitoring." (PMID 34150633, 2021). "A unique feature of ovarian cancer is that a protein called CA-125, encoded by a gene called MUC16, is highly expressed in more than 80% of patients." (PMID 34503075, 2021). "Although MUC16 expression is almost universal in High Grade Serous Ovarian Cancers, engagement of the shed circulating MUC16 antigen (CA-125) presents a theoretical risk of systemic activation and toxicity." (PMID 33936101, 2021). "It is well known that cancer antigen CA125, encoded by the MUC16, is commonly elevated in the serum of women with ovarian cancer." (PMID 33062639, 2020). "The ovarian cancer biomarker MUC16 (also known as CA125) was mutated even more frequently in EC (20%) and CC (29%) samples (compared to 12% in OC), suggesting a common role of MUC16 among gynecologic cancers." (PMID 33194730, 2020). "MUC16 encoded protein CA125 moderates TRAIL-induced apoptosis by decreasing TRAIL receptor R2 expression in epithelial ovarian cancer." (PMID 30670062, 2019). "Mucins normally function to protect and lubricate the epithelium but alterations of MUC16 expression or glycosylation have been associated with the development and progression of ovarian carcinoma." (PMID 31039761, 2019). "CA125 (also known as MUC16) is a type-1 transmembrane glycoprotein that is up-regulated in the blood and tumors of many cancer patients, including ovarian cancer and is associated with poor prognosis." (PMID 29682172, 2018). "Site-specific N-linked glycosylation of the MUC16 ectodomain mediates cell surface interactions, and monoclonal antibodies directed at the ectodomain N-linked glycosylation sites can block ovarian cancer growth." (PMID 29542355, 2018). "More importantly, the characteristic activity profiles of both cancer drugs were retained in MUC16-deficient as well as in MUC16-positive ovarian cancer cells." (PMID 29267342, 2017). "More importantly, when the same supernatants were tested on MUC16-positive OVCAR3 ovarian cancer cells, the MUC16-targeted Meso64TR3 variant was most efficient, while TR3 had almost no appreciable bioactivity, similar to the YFP control." (PMID 29267342, 2017). "The in vitro and in vivo models are consistent with the adverse effects of MUC16 expression levels in serous ovarian cancer and promote the understanding of MUC16 as a pathogenic contributor to the behaviors of ovarian cancer." (PMID 25965947, 2015).
ovarian carcinoma (continued). "Amplification of genomic regions encoding MUC16 in ovarian cancer DNA and over-expression of MUC16 mRNA have been observed in The Cancer Genome Atlas (TCGA) ovarian cancer project and is associated with worse outcome." (PMID 25965947, 2015). "While the expression of MUC16 protein in 3T3 cells was clearly linked to hallmarks of transformation, some fully transformed ovarian cancer cell lines lack MUC16 expression when cultured." (PMID 25965947, 2015). "In The Cancer Genome Atlas ovarian cancer project, MUC16 expression levels are frequently increased, and the highest levels of MUC16 expression are linked to a significantly worse survival." (PMID 25965947, 2015). "Geometric mean levels of preoperative serum CA125 levels among women with ovarian cancer by MUC16 gene polymorphisms, New England-based ovarian case-control study, 2003–2008." (PMID 24551091, 2014). "Current diagnosis of ovarian cancer relies on serum marker CA-125 which is also known as MUC16, a transmembrane protein encoded by the MUC16 gene." (PMID 25299694, 2014). "Among the MUC16 polymorphisms studied, we observed associations between rs2547065 and ovarian cancer risk and between rs12984471 and survival." (PMID 24551091, 2014). "MUC16 knockdown in ovarian cancer cell lines caused increased cytoplasmic localization of β-catenin and E-cadherin, and was linked with greater cellular motility and invasiveness." (PMID 25261375, 2014). "CA 125 (also known as MUC16) is a high molecular weight glycoprotein used mainly as a diagnostic biomarker for ovarian cancer." (PMID 24692843, 2014). "It was found later that mesothelin interacted strongly and specifically with the large glycoprotein MUC16, which is highly expressed in ovarian cancer cells, and that this interaction was mediated by the N-linked oligosaccharides of MUC16." (PMID 19128473, 2009). "TNFα and IFNγ enhance MUC16 expression in breast, endometrial, and ovarian cancer cells through the NFκB pathway, with this upregulation linked to immune regulatory factor activity, indicating that MUC16 modulation may benefit treatment." (PMID 38361923, 2024). "MUC16 is often mutated in ovarian cancer, gastric cancer and other tumor tissues." (PMID 38733174, 2024). "Binding between tumor cells via MSLN-MUC16 interaction—the n-linked glycochain of MUC16 is a necessary condition for interaction—may provide the basis for epithelial ovarian cancer metastasis." (PMID 38758220, 2024). "Proteolytic cleavage of MUC16 releases CA-125 into the bloodstream, retaining the membrane-associated C-terminal on the cell surface; CA-125, a biomarker for ovarian cancer, is targeted by emerging therapies such as Chimeric Antigen Receptor (CAR) T cells and antibody-drug conjugates (ADCs)." (PMID 38361923, 2024). "Hence, the frequency and hotspot mutations in the genes NCOR2, CIITA, MUC4, and MUC16 point towards their role in driving oncogenesis in all ovarian cancer histotypes." (PMID 37091785, 2023). "Our study found that MUC16 stimulation of neutrophils might be a cause of the systemic hyperinflammatory state in ovarian cancer patients." (PMID 37644468, 2023). "Considering that MUC16 and its receptor were associated with inflammation and neutrophil infiltration in ovarian cancer, we speculated that the stimulation of MUC16 might be responsible for the alterations of neutrophil immunophenotype." (PMID 37644468, 2023). "MUC16 is implicated in ovarian cancer chemoresistance; however, the mechanism of MUC16-mediated chemoresistance remains unknown." (PMID 36552994, 2022). "Increased MUC16 expression is associated with poor prognosis in patients with ovarian cancer." (PMID 35628495, 2022). "More detailed future investigations of the mechanism underlying transactivation of MUC16/CA-125 in ovarian cancer cells may yield additional novel targets for ovarian cancer treatment." (PMID 34503075, 2021).
ovarian carcinoma (continued). "Moreover, HE4 expression is lower than MUC16 in benign gynecological conditions and low-malignant potential tumours and HE4 is found in a fraction of endometrial and ovarian cancers which are deficient for MUC16 expression." (PMID 26509158, 2015). "One of four MUC16 SNPs, rs2547065, was associated with increased risk for ovarian cancer." (PMID 24551091, 2014). "In the NECC study, one of the four MUC16 polymorphisms was associated with ovarian cancer risk." (PMID 24551091, 2014). "Additionally, studies show that inflammatory cytokines TNFα and IFNγ can stimulate MUC16 expression in breast cancer, endometrial cancer, and ovarian cancer cells via NFκB, and in these cancer tissues, increased MUC16 expression is associated with elevated cytokine levels." (PMID 38361923, 2024). "In addition to an increased expression, some genes were also downregulated by the overexpression of FGF14, such as COL11A1 which encodes the α1 chain of collagen XI and MUC16, a well-established biomarker used to monitor the progression and recurrence of ovarian cancer." (PMID 32707902, 2020). "Serum CA-125, also referred to as cancer antigen-125 or mucin 16 (MUC16), is a glycoprotein biomarker found in the blood that is commonly used in clinical practice as a marker for ovarian cancer." (PMID 39996185, 2025). "In ovarian cancer, MUC16-targeted MSLN-CAR T cells showed strong cytotoxicity against MUC16-positive OVCAR3 cells in vitro and reduced tumor volumes in mouse models, with peritoneal delivery achieving sustained remission." (PMID 41029427, 2025). "Clinically, sialic acid-rich glycoconjugates serve as established biomarkers (CA19-9/SLex in pancreatic cancer; CA125/MUC16 in ovarian cancer; CA15-3/MUC1 in breast cancer), while specific sialyltransferases show prognostic potential." (PMID 41154604, 2025). "MUC16 promotes ovarian cancer progression by inducing an inflammatory and immunosuppressive neutrophil phenotype and playing a critical role in immune modulation and disease prediction." (PMID 40821814, 2025). "Using the XnCC technique, ovarian cancer derived sEVs were selectively captured on a column chip coated with a MUC16 monoclonal antibody, enabling differentiation between HGSOC patients and healthy individuals." (PMID 40008006, 2025). "Ovarian cancers often overexpress a range of TAAs such as FRα, mucin 16 [MUC16; cancer antigen 125 (CA-125)], and mesothelin, making them ideal targets for bsAb development." (PMID 41211166, 2025). "The mannose receptor (CD206), which is highly expressed on TAMs in ovarian cancer, binds to the MUC16-STn complex, resulting in the increased secretion of the anti-inflammatory cytokine IL-10 and suppression of T-cell chemokine CCL3." (PMID 41383589, 2025). "Other studies have shown that 80% of epithelial ovarian cancer express mucin 16 (MUC16), whose extracellular segment is cleaved and released into the peripheral blood, serving as a well-known tumor marker." (PMID 40092990, 2025). "Anti-MUC16 ADCs are emerging as a promising therapeutic strategy for ovarian cancer, particularly due to the overexpression of MUC16 (also known as CA125) in many ovarian tumors." (PMID 41347223, 2025). "MUC16 constitutes a target for the development of ADCs in ovarian cancer because of its overexpression in most epithelial tumors." (PMID 40722601, 2025). "Taken together, ovarian cancer cells derived from patients with progression of disease on MUC16/CA125-directed BITEs showed decreased levels of CA125 expression and expression of EMT markers." (PMID 41413213, 2025). "In monocytes and NK cells, the MUC16-STn antigen-Siglec-9 ternary complex activates the immune checkpoint network, inhibiting NK cell activation and correlating with reduced ovarian cancer patient survival." (PMID 41383589, 2025).
ovarian carcinoma (continued). "To evaluate the mechanisms of resistance to MUC16-directed bispecific T-cell engagers (BITEs), we consented patients with platinum resistant ovarian cancer who had progressed on a MUC16- BITEs clinical trial to our tissue collection protocol." (PMID 41413213, 2025). "Deep sequencing analysis of the populations, followed by bioinformatics comparison, identified a candidate peptide, DISGTNTSRA, which exhibited sequence homology with CA125 (MUC16), a widely recognized ovarian cancer biomarker." (PMID 40969760, 2025). "Another important focus is developing integrated safety switches, such as the EGFR safety switch in ovarian cancer MUC16 CAR-T." (PMID 40969260, 2025). "In fact, several MUCs are currently used as biomarkers in the clinic, such as MUC1 (CA15-3) in breast cancer and MUC16 (CA125) in ovarian cancer." (PMID 40885395, 2025). "In conclusion, we propose that in a hypoxic tumor microenvironment, target-antigen downregulation, EMT transformation, and VEGF-secretion cooperatively mediate resistance to MUC16 BITE-medicated cytotoxicity in epithelial ovarian cancer cells." (PMID 41413213, 2025). "In both ovarian cancer cell lines, serum from patients who had progressed on MUC16 BITEs suppressed cytotoxicity." (PMID 41413213, 2025). "In ovarian cancer, the upregulation of MUC16 activates the PI3K/Akt signaling pathway and promotes the expression of mesenchymal markers, such as N-cadherin, vimentin, and Snail, leading to increased proliferation, invasion, and metastasis." (PMID 40699805, 2025). "An anti-MUC16/CA125 antibody-bound nanotherapeutic implant drug delivery system improved the survival rate in an ovarian cancer mouse model." (PMID 41361823, 2025). "Ubatamamb is a human bispecific antibody that binds to overexpressed mucin 16 glycoprotein (MUC16) on ovarian cancer cell surfaces and CD3-activated T cells." (PMID 39534871, 2024). "Genes that contributed to the most variation between subtypes included known biomarkers and master regulators of ovarian cancer subtypes (MUC16 and PAX8) and many keratin and cadherin genes (KRT19, KRT7, KRT8, CDH6, and CDH1)." (PMID 39131380, 2024). "Given the high specificity and selectivity of MUC16 and MSLN as diagnostic markers, they have very high potential as theranostic targets to diagnose, treat, and monitor ovarian cancers." (PMID 40836974, 2024). "Given the importance of their interaction for the tumorigenicity of ovarian cancer cells, MUC16 and mesothelin have emerged as putative targets for developing treatments for peritoneal metastasis in epithelial ovarian cancer." (PMID 38637885, 2024). "Circular MUC16 (CircMUC16) is overexpressed in epithelial ovarian cancer tissues, and its expression is related to the stage and grade of ovarian cancer." (PMID 38758220, 2024). "The Mucin 16 (MUC16) antigen has been reported in 70% of ovarian cancer and a clinical trial is also evaluating the efficacy and safety of CAR-T cells targeting MUC16 after standard chemotherapy." (PMID 38892913, 2024). "The results showed that the anti-MUC16 ADC had a tolerable safety profile and encouraging antitumor activity in patients with platinum-resistant ovarian cancer with high MUC16 expression." (PMID 38539161, 2024). "The most prominent examples are CA125, also known as MUC16 for ovarian cancer, CA19-9 for pancreatic cancer, and KL-6 (also known as MUC1) for breast and lung cancer." (PMID 39767713, 2024). "PDAC tumor tissues have significantly increased gene expression of MUC16 compared to normal pancreas tissue but decreased expression compared to ovarian cancer (TCGA)." (PMID 39346763, 2024). "In 2023, CAR-T cells secreting BiTEs were designed to target two tumor antigens highly expressed in ovarian cancer cells: the cell surface Muc16 (4H11) and the intracellular Wilms tumor 1 (ESK1)." (PMID 39711794, 2024).